MYOC (myocilin)
Diseases named in the same sentence as MYOC in open-access papers (continued):
Sharing a sentence is not in itself a finding about the gene and the disease.
glaucoma (continued). "For example, the first pathogenic mutation for primary open-angle glaucoma has been identified in the myocilin gene." (PMID 37106597, 2023). "Taken together, our results motivate MYOC genotyping and subsequent early clinical monitoring of individuals with susceptible alleles for hallmarks of glaucoma pathogenesis." (PMID 36579626, 2023). "When the protein expression pattern of human TM cell-derived EVs was examined and compared to that of EVs purified from urine as a control, it showed an enrichment of the glaucoma-associated protein myocilin." (PMID 37113676, 2023). "In this study, we identified a causal nexus between the glaucoma-associated gene MYOC and Wnt signaling components AXIN2 and sFRP1 in DEX-treated HTM cells." (PMID 37368816, 2023). "MYOC is known as a glaucoma-associated protein and is produced in mesenchymal stem cells, stimulating their osteogenic differentiation." (PMID 36834493, 2023). "In an earlier section, we described a publication that reported on the amino acid sequences of the glaucoma-associated genes myocilin and optineurin." (PMID 37760829, 2023). "Illustrative of the inherent challenges in identifying disease variants in the case of a toxic gain of function like myocilin-associated glaucoma, there are often conflicting annotations of pathogenicity in the literature and in gnomAD." (PMID 36579626, 2023). "Predicting phenotype from genotype is particularly challenging in situations in which there is a toxic gain of function, such as protein aggregation seen in myocilin-associated glaucoma." (PMID 36579626, 2023). "Together, our data indicates, LV_crMYOC targets MYOC gene editing in TM and rescues a mouse model of myocilin-associated glaucoma." (PMID 38196579, 2023). "The olfactomedin domain of myocilin presents a five-bladed β-propeller globular structure and is affected by most glaucoma-related mutations." (PMID 36077382, 2022). "Treatment with phenylbutyric acid (PBA), a chemical chaperone that promotes protein folding and alleviates protein aggregation thus reducing ER stress, successfully prevents TM cell death and lowers IOP in glaucoma models associated with MYOC mutations." (PMID 35346303, 2022). "From 21 glaucoma disease-associated genes with measurable expression, 2 were upregulated (MYOC and FOXE3) and five were downregulated (SH3PXD2B, NF1, SBF2, ADAMTS17, and FOXC1)." (PMID 35348588, 2022). "Myocilin is an enigmatic glaucoma-associated glycoprotein whose biological role remains incompletely understood." (PMID 36077382, 2022). "In order to confirm the protective effect and functionally evaluate this finding, we employed a distinct mouse model of glaucoma that is reliant upon adenoviral-mediated expression of a pathogenic variant of human myocilin in the trabecular meshwork of mice." (PMID 35204782, 2022). "While MYOC remains the best understood and most investigated gene linked to glaucoma, in the years since many other gene linkages have been identified." (PMID 35624748, 2022). "She had a strong family history of glaucoma in multiple first-degree relatives with an identified novel variant of MYOC." (PMID 38868171, 2022). "Loss-of-function, overexpression and/or misexpression of myocilin in mouse models have been used to investigate its role in glaucoma pathogenesis and the biological pathways in which this protein is involved." (PMID 36077382, 2022). "MYOC is a common pathogenic gene for primary open-angle glaucoma and encodes the protein named myocilin." (PMID 36267417, 2022). "We have already discussed the many genes that have been linked to glaucoma, and in particular, MYOC." (PMID 35624748, 2022).
glaucoma (continued). "The olfactomedin domain of myocilin folds like a globular five-bladed β-propeller and contains most glaucoma-causing variants." (PMID 33573230, 2021). "Our analysis shows there is a weak to moderate correlation between the stability of mutated myocilin and age at glaucoma diagnosis of those patients who have the mutations." (PMID 34828408, 2021). "An interesting strategy for the discovery of glaucoma biomarkers would include proteomics and/or metabolomics studies on the sera of families with Mendelian inheritance of glaucoma, including those with myocilin mutations causing 3–4% of POAG." (PMID 34439995, 2021). "TGFβ2 levels (pro and active) are elevated both in steroid-induced glaucoma and myocilin-associated glaucoma, suggesting that TGFβ2 signaling is an important mediator in OHT models." (PMID 34830390, 2021). "Our study indicates that although many individuals with MYOC mutations have ER stress in the TM, not every individual with an MYOC mutation will respond with a stress-induced, high-fold increase in myocilin expression and develop myocilin-associated glaucoma." (PMID 34828408, 2021). "Following isolation of the Myocilin (MYOC) gene, the clinical manifestation of glaucoma has been associated with a genetic predisposition." (PMID 34439851, 2021). "The melting temperatures of the wild-type and several glaucoma-associated mutated OLF domains of myocilin were experimentally determined." (PMID 34828408, 2021). "As an example, we would expect to find 27 cases carrying a stop-gain mutation (OR = 5.1, MAF = 0.0013) on MYOC per 1000 glaucoma cases from the lowest PB risk bin." (PMID 34285202, 2021). "We confirmed the correlation between the melting temperatures of glaucoma-associated myocilin mutants and age at glaucoma diagnosis, but the correlation we obtained is weak." (PMID 34828408, 2021). "Pathology associated with disease conditions such as protein misfolding (myocilin-associated glaucoma) or increased synthesis (steroid or TGFβ2-induced glaucoma) can disturb protein homeostasis in the ER, resulting in ER stress." (PMID 34830390, 2021). "One particular MYOC mutation, Gln368Stop (dbSNP accession number: rs74315329), is the most common genetic mutation, causing glaucoma by increasing IOP." (PMID 34439851, 2021). "Over the past two decades myocilin research has provided insight into the structure, expression and association with glaucoma of this protein." (PMID 33573230, 2021). "One of them is the impact of β-catenin (component of the cell adhesion and transducer of extracellular signals) on gene expression; for example, the most common glaucoma-causing gene, MYOC, influences the intracellular levels of this molecule." (PMID 34348663, 2021). "In this study, we investigated if transplanted stem cells are able to rescue a glaucoma mouse model with transgenic myocilin Y437H mutation and explored the possible mechanisms." (PMID 33506763, 2021). "Chronic ER stress is known to play a key role in the elevation of IOP in myocilin-associated glaucoma." (PMID 33539326, 2021). "We therefore conclude that genetic analysis of MYOC mutations alone cannot be used to accurately predict age at glaucoma diagnosis." (PMID 34828408, 2021). "Mutations in the gene encoding myocilin (Myoc) have been confirmed to be associated with glaucoma which are responsible for 4% of adult-onset POAG and 10% of juvenile-onset POAG." (PMID 33506763, 2021). "Disease-causing myocilin mutants are secretion incompetent, and improving secretion of mutant myocilin via sodium 4-phenylbutyate rescues glaucoma in Tg-MYOCY437H mice." (PMID 33539326, 2021). "For myocilin, a protein prone to misfolding that is associated with glaucoma and an emerging player in other human diseases, currently available antibodies are unable to differentiate among the numerous disease-associated protein states." (PMID 34384785, 2021).
glaucoma (continued). "The ability to track different forms would help understand familial mutations that predispose the carrier to myocilin misfolding and heritable glaucoma." (PMID 34384785, 2021). "Nevertheless, approximately 3% to 5% of the 70 million people affected by glaucoma have MYOC mutations." (PMID 34828408, 2021). "The presence of MYOC mutations would be clinically instructive for patients’ glaucoma treatment plans." (PMID 34828408, 2021). "Several of the differentially expressed genes have previously been reported to be associated with elevated IOP and/or glaucoma, including MYOC, ADAMTS10, LTBP2, LOXL1, TGFBR3, CYP1B1, and EFEMP15,28,43–45." (PMID 34385434, 2021). "We included 40 published studies with at least one glaucoma patient with one of these 20 MYOC mutations and information on age at glaucoma diagnosis." (PMID 34828408, 2021). "This is consistent with a study describing in cell culture experiments that αB-crystallin can bind to a myocilin variant, which is closely associated with glaucoma development, thereby promoting degradation of this complex." (PMID 34943212, 2021). "A prior study has used CRISPR-Cas9 to correct one mutation in the myocilin (MYOC) gene associated with the development of glaucoma." (PMID 31981492, 2020). "The normal function of the myocilin protein and pathogenic mutations of MYOC in glaucoma is not well understood." (PMID 32410836, 2020). "Considering limited availability of MYOC-associated POAG donor tissues, this approach offers the possibility of understanding the pathology behind MYOC-associated glaucoma." (PMID 32579557, 2020). "Topical ocular sodium 4-phenylbutyrate (PBA) treatment rescued glaucoma phenotypes in a transgenic mouse model of POAG caused by the Y437H MYOC mutation (Tg-MYOCY437H)." (PMID 32545285, 2020). "In the context of the other established variants in glaucoma, including the protein-truncating variants in MYOC, p.Gln175His and the 57-fold Finnish-enriched p.Arg220Cys variants in ANGPTL7 exert a comparable protective effect." (PMID 32369491, 2020). "Previous genome-wide association studies identified over 10 genes associated with primary open-angle glaucoma, including myocilin (MYOC), optineurin (OPTN) and WD repeat domain 36 (WDR36)." (PMID 32953253, 2020). "Known variants in MYOC are curated and made available online via the ‘myocilin allele-specific glaucoma phenotype database’24." (PMID 30816137, 2019). "The myocilin gene (MYOC) is the most common glaucoma-causing gene, accounting for ~2% of British POAG cases." (PMID 30816137, 2019). "I came across a collection of papers describing the effect of mutations on myocilin, which cause the inherited form of glaucoma, a prevalent and heterogeneous disease leading to irreversible blindness." (PMID 31009450, 2019). "Over 20 years ago, alterations to the protein myocilin were confirmed to be linked to a heritable form of the prevalent eye disease, glaucoma, and 10 years ago, my lab set out to develop a deeper understanding of myocilin in its normal and diseased state." (PMID 31009450, 2019). "Familial, inherited genetic mutations in myocilin, found in populations throughout the world, account for about 3% to 5% of the 70 million cases of glaucoma worldwide." (PMID 31009450, 2019). "The disease is autosomal dominant—it only takes one bad copy of the myocilin gene to cause glaucoma." (PMID 31009450, 2019). "Our work further supports drug discovery efforts to inhibit these interactions as a strategy to treat myocilin-associated glaucoma." (PMID 31484937, 2019). "Myocilin, a glaucoma associated protein, has been found elevated in ocular tissue, in AH of animal models of glaucoma and in humans." (PMID 30673862, 2019). "Mutations in MYOC are a major cause of glaucoma and have been discovered in 3% to 4% of patients with POAG." (PMID 30923720, 2019).
glaucoma (continued). "The MYOC gene encodes the protein myocilin, which is believed to have a role in cytoskeletal function and it has been previously reported in glaucoma." (PMID 30940089, 2019). "This Research Matters article by Raquel Lieberman provides an overview of her lab's basic research on protein myocilin, an eye protein implicated in glaucoma but whose normal function has remained shrouded in mystery for over 20 years." (PMID 31009450, 2019). "Myocilin is an extracellular glycoprotein with a poorly understood biological function and typically known because of its association with glaucoma." (PMID 30557320, 2018). "It has been reported that 8% to 30% of patients with JOAG and 2 to 4% of patients with POAG have disease causing variants in the MYOC gene, evidencing the importance of this gene to glaucoma’s etiology." (PMID 30444892, 2018). "Although the eye and glaucoma have been the primary focus when studying pathological MYOC mutations, there is interest in knowing if MYOC mutations result in pathology in other tissues." (PMID 30395621, 2018). "Myocilin- (MYOC-) dominant gain-of-function mutations have been reported in approximately 4% of all primary open-angle glaucoma (POAG) cases, but 10–33% of juvenile open-angle glaucoma cases harbour a MYOC mutation." (PMID 29853847, 2018). "Mutations in myo-C, the gene encoding myocilin, were identified in some cases of primary open angle glaucoma (POAG)." (PMID 29738436, 2018). "Two candidate genes associated more broadly with other subtypes of glaucoma, myocilin (MYOC), and lysyl oxidase homolog 1 (LOXL1) have shown limited association with PDS/PG." (PMID 29780638, 2018). "The ER-resident Hsp90 isoform, glucose-regulated protein 94 (Grp94), promotes the aggregation of mutant forms of myocilin, a protein associated with primary open-angle glaucoma." (PMID 29263415, 2017). "The present work reveals that FOXC1 is an important regulator of exocytosis and establishes a new link between FOXC1 and MYOC-associated glaucoma." (PMID 28575017, 2017). "Pathogenic MYOC mutations found in glaucoma patients affect MYOC secretion and result in intracellular accumulation of MYOC." (PMID 28575017, 2017). "MYOC is a protein associated with early onset glaucoma, similarly to FOXC1, and is also involved in steroid induced glaucoma." (PMID 28575017, 2017). "For example, mutations in the OLF domain of myocilin were closely associated with primary open angle glaucoma." (PMID 27821182, 2016). "It is believed that in the case of steroid induced glaucoma, over-expression of myocilin is one of the triggering factors for glaucoma causation; however, the notion is still controversial." (PMID 27243976, 2016). "But so far, it is not known if some primates such as baboon and human express these photomedins, whereas some olfactomedin-proteins like myocilin are associated with eye diseases such as glaucoma." (PMID 27821182, 2016). "Of the three genes, MYOC is deemed a direct causative gene leading to glaucoma, accounting for ~1 to 4% of mutations for POAG although the exact roles of OPTN and WDR36 remain to be determined." (PMID 25777973, 2015). "Accumulation of Y437H-myocilin, a mutant myocilin that causes severe glaucoma in people, in the endoplasmic reticulum of transgenic mice leads to activation of the apoptotic pathway and results in a glaucoma phenotype." (PMID 25364714, 2014). "Recently, PBA was shown to prevent disease phenotypes in a mouse model of primary open angle glaucoma caused by a mutation in the myocilin gene." (PMID 24849605, 2014). "Linkage analysis of large pedigrees with Mendelian forms of glaucoma has identified three genes that cause glaucoma (MYOC, OPTN, and TBK1)." (PMID 24883232, 2014). "Glaucoma-causing mutant myocilin and retinitis pigmentosa-associated interphotoreceptor retinoid-binding protein cause endoplasmic reticulum stress due to misfolding and subsequent accumulation in the endoplasmic reticulum." (PMID 24849605, 2014).
glaucoma (continued). "Such association studies have been conducted and replicated in at least a dozen populations across the globe, making the association between myocilin polymorphisms and glaucoma risk one of the best consolidated relationships in human disease genetics." (PMID 25364714, 2014). "Several members of the family have been implicated in various common diseases, notably myocilin in glaucoma and OLFM4 in cancer." (PMID 25364714, 2014). "For example, studies of transgenic mice have provided key insights into the pathogenesis of glaucoma caused by MYOC mutations." (PMID 24883232, 2014). "Despite a widespread expression profile, myocilin’s function remains elusive and mutations in myocilin result in a very limited, but clinically important phenotype of ocular hypertension and glaucoma." (PMID 24367514, 2013). "Significantly, two different point mutations in myocilin that cause glaucoma differentially disrupt the character and timing of myocilin-GPCR interactions." (PMID 24367514, 2013). "Myocilin cleavage is reduced by glaucoma mutations and it has been proposed to participate in intraocular pressure modulation." (PMID 23342144, 2013). "To investigate the incidence of mutations in genes associated with the different phenotypes of glaucoma, we checked for mutations in MYOC and CYP1B1 in a large cohort of a Spanish population." (PMID 23922489, 2013). "Given the universal nature of endocytosis and the very limited phenotype associated with myocilin glaucoma, some level of cell-type or tissue specificity is likely." (PMID 24367514, 2013). "Different mutations within the myocilin gene lead to a variety of glaucoma phenotypes in both juvenile and adult-onset primary open-angle glaucoma, providing further evidence for its role in steroid-induced IOP." (PMID 22536546, 2012). "The Pro370 to Leu (P370L) mutation of myocilin is associated with severe glaucoma phenotypes and Gln368 stop (Q368X) is the most common myocilin mutation reported." (PMID 23028669, 2012). "The overall frequency of glaucoma-causing MYOC mutations in our African American population with POAG was 1.4%." (PMID 22933836, 2012). "As expected, some of these genes coincide with those selected above through other selection means, ratifying the relevance of their potential involvement in the association of MYOC mutants with glaucoma." (PMID 22615763, 2012). "It is believed that in case of steroid induced glaucoma, over expression myocilin is one of the triggering factors for glaucoma causation; however, the notion is still controversial." (PMID 23028769, 2012). "A similar effect was also shown for another methylamine, TMAO, in the correction of myocilin-causing glaucoma." (PMID 22973456, 2012). "It is important to point out that MYOC-causative glaucoma occurs only in heterozygous individuals, and that MYOC forms wild-type/mutant hetero-oligomers which lead to the formation of insoluble aggregates (gain of function)." (PMID 22615763, 2012). "These African American patients carrying myocilin mutations tend to have advanced glaucoma with high IOP and large cup-to-disc ratio." (PMID 22933836, 2012). "We next were interested to determine the ability of the MYOC mutants to alter a set of genes potentially associated with glaucoma and or glaucomatous insult." (PMID 22615763, 2012). "In this study, we further analyzed the involvement of myocilin variants in 450 additional POAG patients with a familial history of glaucoma or high intraocular pressure and have provided a comprehensive analysis of a total of 765 eastern Indian POAG patients." (PMID 22736945, 2012). "The glaucoma phenotype of each of the different MYOC mutation varies, but all of them cause elevated intraocular pressure (IOP)." (PMID 22615763, 2012). "This proves that mutations in the olfactomedin domain are expected to give rise to possible pathogenic glaucoma phenotypes, and explains preponderance of disease causing mutations in MYOC exon 3 coding this domain." (PMID 22736945, 2012).